MCM2 (minichromosome maintenance complex component 2)
Diseases named in the same sentence as MCM2 in open-access papers (continued):
Sharing a sentence is not in itself a finding about the gene and the disease.
cancer (157 papers, 2003 to 2026). A tumor composed of atypical neoplastic, often pleomorphic cells that invade other tissues. "We further selected two representative genes, SPP1 and MCM2 to study the mutation and copy number variation profiles at the pan-cancer level." (PMID 37723560, 2023). "Hub L1 ASP-associated genes CENPU and MCM2 showed a correlation with immune infiltration, clinical T stage, and cancer stemness in pan-cancer." (PMID 37723560, 2023). "Accordingly, MCM2 up-regulation partly reversed CACYBP deficiency’s inhibition against cancer cell viability and invasion." (PMID 37305391, 2023). "Mutations in MCM4 disrupt the functions of MCM2–7, resulting in genomic instability and cancer progression." (PMID 35360518, 2022). "Next, we investigated the mutation rate and the relationship between MCM2 expression and the infiltration of immune-related cells and molecules across cancers." (PMID 35693940, 2022). "MCM2 was overexpressed in a number of cancers and was extensively used as a broad-spectrum diagnostic and prognostic biomarker." (PMID 36303105, 2022). "Association of MCM2 knockdown with increased sensitivity to chemotherapy was detected in many cancers." (PMID 36303105, 2022). "The deficiency of MCM2 was proved to be a driver of tumorigenesis by reducing licensing origins and causing genomic instability, both of which increase cancer susceptibility." (PMID 36303105, 2022). "The prevalence of MCM2 somatic mutations was analyzed to determine the MCM2 mutation rate in clinical samples across 32 cancers." (PMID 35693940, 2022). "The MSIsensor score was much higher in cancers with multiple MCM2 mutations (14.53; 8.90–20.17) than those with missense MCM2 mutations (0.04; 0.07–17.06) and truncating MCM2 mutations (0.03; 0.01–0.05)." (PMID 35693940, 2022). "The MCM2-7 genes are linked to and drive several cancer types in humans, and when mutated in mice result in growth retardation and mortality." (PMID 35737938, 2022). "High risk for progression is driven by a lower level of cg08889930 methylation that results in an overexpression of MCM2, which in turn is associated with cancer progression and poor prognosis." (PMID 33499054, 2021). "Overexpression of MCM2/3/4/5/6/7/8/10 was found to be significantly associated with clinical cancer stage." (PMID 34404366, 2021). "High MCM2 expression in cancers was associated with higher grades, more advanced stages and poor prognosis." (PMID 33499054, 2021). "Association of Mcm2 with clinicopathological characteristics was also observed in other types of cancer including diffuse large B-cell lymphoma and muscle-invasive urothelial cancer." (PMID 29651420, 2018). "To explore this, we used a previously established MCM2-deficient mouse model of cancer, generated by integration of a tamoxifen-inducible form of Cre recombinase downstream of the Mcm2 coding sequence and expression via an internal ribosome entry site (IRES)." (PMID 28915237, 2017). "This view is supported by similar cancer predisposition phenoptypes in mice that are hypomorphic for Mcm2, and which also show premature aging and stem cell defects in certain cell lineages." (PMID 26765334, 2016). "Genetically reducing Mcm2 expression to about 1/3 of normal levels causes stem cell defects and cancer predisposition in mice." (PMID 26765334, 2016). "Depletion of MCM2, -6, or -7 in these mutant cells resulted in deleterious effects such as growth retardation, inhibited cell proliferation, genomic instability, and cancer predisposition." (PMID 25386362, 2014). "The dominant inheritance of the cancer phenotype observed in Sdl contrasts to previous studies of mice harboring Mcm2 (Mcm2IRES-CreERT2) or Mcm4 (Mcm4chaos3) hypomorphic alleles in which tumors were only observed in the homozygous state." (PMID 23133403, 2012).
cancer (continued). "To identify if there is a critical MCM threshold for cancer susceptibility, we aged a cohort of Mcm2Gt/+ mice, representing approximately intermediate MCM2 levels." (PMID 20838603, 2010). "Deregulated levels of MCM2-7 complex subunits are also closely associated with cancer." (PMID 39184446, 2024). "Importantly, ectopic expression of CDC6 effectively reduced the defects in cell proliferation of cancer cells and restored the decreased level of chromatin-bound MCM2 in vitro caused by OTUD6A knockdown." (PMID 38685067, 2024). "The importance of MCM2 in DNA replication and cell proliferation makes it a highly specific and sensitive marker, which has diagnostic and prognostic significance in various human malignant tumors 59-63." (PMID 36778110, 2023). "Cancers arising in different anatomic sites are also associated with minichromosome maintenance complex component 2 (MCM2), MCM4, and minichromosome maintenance complex component 6 (MCM6) overexpression, but there is not much information about the role of MCM4 in PC." (PMID 36329790, 2023). "Overexpression or mutation in MCM2-7 genes is linked to and may drive several cancer types in humans." (PMID 35737938, 2022). "In addition, upon further exploration of the critical role of MCM2 in promoting cancer progression, we performed cell and molecular experiments to verify the associations between MCM2 expression and the activities of SKCM cell lines." (PMID 35693940, 2022). "MCM2 mutated in many cancers, except ACC, CHOL, DLBC, KIRP, PCPG, TGCT, THCA, and UVM." (PMID 35693940, 2022). "In this article, we systematically provide the oncogenic role and possible mechanism of MCM2 across cancers through a combined analysis of genomics, transcriptomics and proteomics to explore the potential diagnostic, prognostic and therapeutic value of MCM2 in various cancers." (PMID 35693940, 2022). "Moreover, the TMB was significantly different among cancers with multiple MCM2 mutations (364, 313.9–414.08), truncating MCM2 mutations (17.5, 8.84–30.89) and missense MCM2 mutations (35.63, 10.65–90.36)." (PMID 35693940, 2022). "This study explored the oncogenic role of MCM2 across cancers, provided data on the underlying mechanisms of these cancers for further research and demonstrated that MCM2 may be a promising target for cancer immunotherapy." (PMID 35693940, 2022). "Aberrant expression of MCM2, whether upregulation or downregulation, could both increase cancer risk and promote cancer progression." (PMID 36303105, 2022). "We also investigated the gene expression characteristics of MCM2 which presented a high mutation rate, indicating that MCM2 may be a potential marker for diagnosing various cancers." (PMID 35693940, 2022). "Moreover, MCM2 can activate or suppress diverse cancer-related pathways and is implicated in EC drug sensitivity." (PMID 34859821, 2021). "Mcm2 expression is known to be downregulated when homozygous Mcm2-CreER mice (Mcm2CreER/CreER) are used, resulting in the loss of ASCs/PCs and the formation of cancer (likely because of genome instability)." (PMID 31041783, 2019). "In a mouse model for cancer driven by deficiency in Mcm2, genomic deletions can occur." (PMID 28640831, 2017). "In addition, U1 snRNA over-expression caused significantly increased expression of Pcna, Mcm2 and Ki-67 by 10.44, 12.8 and 2.13 fold changes in Hela cells, which suggested that U1 snRNA over-expression promoted proliferation in cancer cells." (PMID 29348872, 2017). "However, a conundrum is why Chaos3 mice or mice deficient for Mcm2 are cancer prone, since they would be expected to be more susceptible to undergoing senescence." (PMID 26765334, 2016).
cancer (continued). "Some of the phosphoproteins identified in this study have been previously implicated in cancer malignancy such as Mcm2 and adenylyl cyclase associated protein (CAP1), while little information is available on some of the other potential targets including small acidic protein." (PMID 20661426, 2010). "It is rational that MCM2 may serve as a reliable diagnostic and prognostic marker in cancers." (PMID 36303105, 2022). "However, few articles have systematically reported the pathogenic roles of MCM2 across cancers." (PMID 35693940, 2022). "Recently, the minichromosome maintenance (MCM) protein complex, consisting of six highly conserved proteins (MCM2-7), has been highlighted for its prognostic significance in several cancers." (PMID 40445576, 2025). "TOP2A and MCM2 were present in higher amounts per cell in PCS lysates compared to cancer cell lines." (PMID 40507244, 2025). "MCM2 dysfunction, by affecting DNA replication and cell proliferation, contributes to the development of cancer." (PMID 39940790, 2025). "Among the upregulated genes, we observed strong overexpression of TPX2 and MCM2, which regulate cell proliferation during cancer development." (PMID 38584841, 2024). "MCM2 is highly expressed in malignant carcinomas, including CSCs, and contributes to the malignancy of various cancers." (PMID 38454443, 2024). "MCM2 is a core subunit of the essential eukaryotic DNA helicase, which plays a vital role in DNA replication and is considered a potential biomarker for cancer diagnosis, prognosis, and chemotherapy sensitivity." (PMID 38370368, 2024). "MCM2 is a protein involved in the cell cycle and plays a role in cancer growth and differentiation by binding to six members of the MCM subfamily." (PMID 38454443, 2024). "Elevated MCM2 has been found in pan-cancer and is associated with TMB, stage, immunotherapy response and dismal prognosis, indicating that MCM2 acts as a potential target for cancer immunotherapy." (PMID 38466483, 2024). "Some studies demonstrated that MCM2 can be regarded as similar to ki-67 and thus serves as measuring cancer cell proliferation." (PMID 38512482, 2024). "IMMT levels positively correlated with biomarkers linked to cancer proliferation (KI67, PCNA, and MCM2) and with key regulators of the cell cycle (CDK4, CDK2 and CDK1)." (PMID 36899366, 2023). "MCM2 is thought to be a sensitive biomarker for cancer and a potential novel therapeutic target for cancer treatment." (PMID 36769104, 2023). "We also evaluated the predictive power of MCM2 and constructed ROC curves to assess the ability of MCM2 to predict the prognosis of patients with various cancers." (PMID 35693940, 2022). "Cumulative evidence suggests that MCM2 proteins play a crucial role in maintaining the malignancy of cancer cells by interacting with several proteins." (PMID 35693940, 2022). "The protein levels of MCM2 were significantly overexpressed in the cancer cell lines A375, A875, M14 and SK28 compared to the normal human skin melanocyte line PIG1, indicating that MCM2 was extremely overexpressed in A375 and SK28 cells." (PMID 35693940, 2022). "In this review, the structure and biological function of MCM2 will first be summarized, followed by its role in cancer development, diagnosis, and prognosis." (PMID 36303105, 2022). "With the in-depth study of MCM2, we will become more confident to illuminate the role of MCM2 as an effective biomarker and therapeutic target in cancers and even bring translational benefits to patients." (PMID 36303105, 2022). "Molecular subtypes were observed to be related to MCM2 expression in eight cancers: BRCA, COAD, HNSC, LIHC, OV, SKCM, STAD and UCEC." (PMID 35693940, 2022). "Here, we evaluated the correlation between three classic ICGs, CD274, CTLA4 and PDCD1, and MCM2 expression in 40 TCGA cancers." (PMID 35693940, 2022). "Previous studies have reported that MCM2 plays a pivotal role in cell proliferation and cancer development." (PMID 35693940, 2022).
cancer (continued). "One of the strongly downregulated genes was MCM2, which was observed to have a potential role in promoting cancer cell growth in RA-resistant cells." (PMID 35693940, 2022). "Taken together, our results indicate that MCM2 is a potential biomarker for diagnosis and prognosis across cancers and a promising molecular target for treating SKCM." (PMID 35693940, 2022). "The transcription levels of MCM2 in different cancers and corresponding adjacent normal tissues were analyzed with R studio, combining data from TCGA and GTEx." (PMID 35693940, 2022). "In the current study, we analyzed the expression and sublocalization of MCM2 in 33 cancers and found that MCM2 was significantly upregulated in 30 cancers and that mainly located in the nucleus of cells." (PMID 35693940, 2022). "Of all the MCMs, MCM2 is the most researched protein in cancer, which makes it a promising biomarker for diagnosing cancers." (PMID 35693940, 2022). "Most of these cancers had a significant difference in MCM2 transcription between normal tissue and different cancer stages." (PMID 35693940, 2022). "The overexpression of MCM2 was detected in multiple types of cancers, and the dysfunction of MCM2 was correlated with the progression and poor prognoses of malignant tumors." (PMID 36303105, 2022). "According to the altered expression of MCM2 and its correlation with clinicopathological features of cancer patients, MCM2 was thought to be a sensitive biomarker for cancer diagnosis, prognosis, and chemotherapy response." (PMID 36303105, 2022). "MCM2 is highly expressed in solid tumors and silenced in normal samples and a possible prognostic marker and therapeutic target in a group of cancers." (PMID 35693940, 2022). "The IHC results of these cohorts all suggested that MCM2 expression in cancer was significantly higher than that of the paraneoplastic tissues, and that MCM2 expression in paraneoplastic tissue was also higher than that of normal liver tissues." (PMID 36243809, 2022). "Here, we explored the role of MCM2 in cancer diagnosis, therapy and prognosis, as well as its interaction with other genes and proteins and immune infiltration across cancers." (PMID 35693940, 2022). "We found that MCM2 is not only significantly upregulated in 33 types of human cancers but also differentially expressed in the different immune subtypes and molecular subtypes of eight cancers." (PMID 35693940, 2022). "As predicted, we found that the expression levels of MCM2 were much higher in cancer cells than in normal cell lines and that downregulating MCM2 in SKCM cells significantly inhibited cell proliferation." (PMID 35693940, 2022). "Collectively, our study revealed that MCM2 is a promising biomarker for cancer diagnosis, therapy design and prognosis and follow-up." (PMID 35693940, 2022). "Many cancers showed a positive correlation between MCM2 expression levels and malignant progression of cancers in accordance with the inherent function of MCM2 in cell proliferation." (PMID 36303105, 2022). "Inhibition of the Cdc7/Dbf4 kinase activity can affect specific phosphorylation sites on MCM2 in cancer cells." (PMID 34975331, 2022). "In summary, these findings illustrated the different phosphorylation sites of MCM2 and highlight potential loci for further molecular assays in a subset of cancers." (PMID 35693940, 2022). "Overexpression of CDK1, MCM2, E2F2, PLK1, CCNB1/2, BUB1, BUB1B, CDC25 has been associated with aberrant proliferation in many cancer types including HCC." (PMID 33499054, 2021). "Altered MCM2 expression was shown to signify cell-cycle deregulation, which is necessary for the initiation and progression of cancers." (PMID 34490114, 2021). "MCM2 was studied in a variety of human malignant tumors and was related to the histopathological grade of many." (PMID 34174849, 2021).
cancer (continued). "Diagnostic accuracy estimation of differentially expressed genes showed that a gene panel consisted of CALU, AURKA, and MCM2 was able to successfully distinguish cancer tumors from healthy samples." (PMID 32469983, 2020). "Last, MCM2, a key player in DNA replication, is over-expressed in highly proliferating undifferentiated cancer cells." (PMID 33153038, 2020). "Altered MCM2 expression signifies cell-cycle deregulation, which is necessary for the initiation and progression of cancer." (PMID 32058552, 2020). "Western blot analysis of CALU, AURKA, and MCM2 proteins showed that the level of all of these candidate biomarkers was statistically increased through normal–carcinoma transition in both types of cancers." (PMID 32469983, 2020). "Increasing evidence has confirmed that MCM2 can be used as a biomarker for the diagnosis and prognosis of various cancers." (PMID 32420375, 2020). "In previous studies, the heterohexameric complex composed of MCM2-7 has been well summarized in human cancer cells." (PMID 32964028, 2020). "MCM2 is an essential DNA replication factor that is highly expressed in cancer cells as well as in the oocyte and is highly involved in resumption of meiosis in mammalian oocytes." (PMID 31787077, 2019). "Among these genes, CDCA5, FOXM1, KIF15, MCM2, and ZWINT were the most reported genes associated with cancer progression, including EOC." (PMID 31708970, 2019). "MCM2, 3 and 4 were also observed to be highly expressed in cancer cells compared to normal cervical epithelial cells." (PMID 31653153, 2019). "The role of phosphorylated MCM2 in cancer is also corroborated by a phospho-proteomic analysis of liver cell lines with different proliferation potential." (PMID 31784636, 2019). "Increased levels of Mcm2 expression have been detected in a variety of cancers, and it is often accompanied with overexpression of Ki-67, a representative marker for cell proliferation." (PMID 29651420, 2018). "Previous studies using human samples have established MCM2 as a proliferation marker of cancer cells." (PMID 29963273, 2018). "When the expression levels of Mcm2 were reduced to one-third of wild-type levels, the average life span of mice decreased markedly due to high incidence of cancers, and the majority of them were T- and B-cell lymphoma." (PMID 29651420, 2018). "Up to this point, it is interesting to note that in both cell lines, MP-HX downregulated all six top-ranked genes (PLK1, MCM2, MCM3, MCM7, MCM10 and SKP2) that were proposed to be cancer-associated (Wu, Zhu & Zhang, 2012)." (PMID 30042885, 2018). "To develop an MCM2-targeted therapy, we proposed a method for efficiently introducing the gp70 protein into cancer cells." (PMID 29963273, 2018). "Here, we highlight the function and mechanism of MCM2–7 protein phosphorylation in human cancer cells." (PMID 30062004, 2018). "It is interesting to note that all six top-ranked genes proposed to be cancer-associated (PLK1, MCM2, MCM3, MCM7, MCM10 and SKP2) were downregulated by MP-HX in both cell lines." (PMID 30042885, 2018). "This was further supported by subsequent studies that reported elevated levels of other Mcms (Mcm2 and Mcm5) in various types of cancers." (PMID 29651420, 2018). "Although MCM2 expression was mainly localized to the nuclei as in other cancers, a few cases exhibited cytoplasmic localization of MCM2." (PMID 29963273, 2018). "The same study showed that levels of microRNA (miR)-1296 expression was reduced in carcinoma samples and miR-1296 targeted Mcm2 mRNA probably by binding to the 3′ untranslated region (3′ UTR) of Mcm2." (PMID 29651420, 2018). "We further examined MCM2 expression in 14 cancer types from TCGA, and found MCM2 is significantly highly expressed in all cancerous tissues in comparison to their adjacent normal tissues." (PMID 29038488, 2017).